CDC6 (cell division cycle 6)
Diseases named in the same sentence as CDC6 in open-access papers (continued):
Sharing a sentence is not in itself a finding about the gene and the disease.
breast invasive carcinoma (1 paper, 2023). "The analysis of the expression of RRM2, CDC6, and TOP2A in normal and tumour breast invasive carcinoma using GEPIA showed significant increased expression of RRM2, CDC6 and TOP2A in tumour samples as compared to normal tissue." (PMID 36997866, 2023).
breast tumors (1 paper, 2007). "To this end, we first found significant association of the expression profiles of four genes, CDC2, CKS2, DNA2L, and CDC6, with ERβ transcript levels in the breast tumors, consistent with the inverse correlation (high ERβ; low cell cycle/DNA replication genes) observed in the cell line model." (PMID 17428314, 2007).
ciliopathy (1 paper, 2021). A genetic disorder of the cellular cilia or the cilia anchoring structures, the basal bodies, or of ciliary function. "An intriguing connection between MGS and ciliopathy is based on the observation that depletion of ORC1, ORC4, ORC6, CDT1 and CDC6 leads to reduced primary cilia formation." (PMID 33477564, 2021). "When fibroblasts were depleted for ORC1, ORC4, ORC6, CDT1 and CDC6, primary cilia formation was impaired, suggesting that MGS symptoms might constitute a ciliopathy." (PMID 33477564, 2021).
colon adenocarcinoma (1 paper, 2023). "The results indicated a positive association between CDC6 expression and the presence of CD8+ T cells, B cells, neutrophils, and dendritic cells (DCs) in colon adenocarcinoma (COAD)." (PMID 37945594, 2023).
cyst (1 paper, 2021). A sac-like closed membranous structure that may be empty or contain fluid or amorphous material. "Cluster 7 was annotated as proliferating cholangiocytes given its high G2/M cell cycle score and expression of BRCA2, CDC6 and CDK1 in both monolayer and cyst cells." (PMID 34764255, 2021).
endometrial carcinoma (1 paper, 2024). A malignant tumor arising from the epithelium that lines the cavity of the uterine body. "The effect on the survival rate of patients with endometrial carcinoma was more significant when a missense mutation of CDC6 occurred than in patients with high CDC6 expression." (PMID 39684684, 2024). "In summary, abnormal CDC6 expression plays an important role in the occurrence of endometrial carcinoma." (PMID 39684684, 2024). "We reached a similar conclusion in our evaluation of the effect of CDC6 on endometrial carcinoma." (PMID 39684684, 2024). "In conclusion, in PCOS and EC sample databases, CDC6 can be screened for since it is highly expressed in endometrial carcinoma and may play an important role in the progression of PCOS to EC." (PMID 39684684, 2024). "In summary, CDC6 expression is closely related to the infiltration of the TME, suggesting that CDC6 may affect the immune response in endometrial carcinoma." (PMID 39684684, 2024). "Therefore, the role of CDC6 in the progression of polycystic ovary syndrome to endometrial cancer by promoting immune infiltration may serve as a new tumor prognostic biomarker and a potential immunotherapy target." (PMID 39684684, 2024). "Therefore, we further determined the expression levels of CDC6, EGFR, and HAUS6 during PCOS carcinomatosis to endometrial carcinoma." (PMID 39684684, 2024). "CDC6 may exert a carcinogenic effect on PCOS through the PI3K-AKT pathway, leading to the eventual development of endometrial carcinoma." (PMID 39684684, 2024).
endometriosis (1 paper, 2014). The growth of functional endometrial tissue in anatomic sites outside the uterine body. "CDC6 is an ATPase associated with cell cycle progression but has not been described in the pathophysiology of endometriosis." (PMID 25207642, 2014).
epilepsy (1 paper, 2023). A brain disorder characterized by episodes of abnormally increased neuronal discharge resulting in transient episodes of sensory or motor neurological dysfunction, or psychic dysfunction. "Interestingly, variants of unknown significance that fit the syndromic phenotype were identified in CDC6 in a patient with syndromic epilepsy by TE." (PMID 38125836, 2023).
epithelial dysplasia (1 paper, 2008). "Real-time PCR for CDC6 revealed that there was statistically significant overall difference in CDC6 expression among the mild, moderate and severe epithelial dysplasia and SCC of the tongue (p = 0.043; Kruskal-Wallis test)." (PMID 19116018, 2008). "Likewise, the mean level of CDC6 was markedly higher in SCC of the tongue than in the mild epithelial dysplasia." (PMID 19116018, 2008). "In this study, we found that CDC6, CDT1, MCM2 and CDC45 mRNA expression analyzed by quantitative real-time PCR are significantly higher in malignant SCC than mild precancerous epithelial dysplasia, and the expression levels in general increase with increasing grade of dysplasia." (PMID 19116018, 2008). "In addition, the mean level of CDC6 was markedly higher in SCC of the tongue and severe epithelial dysplasia than in the mild epithelial dysplasia (p = 0.02 and 0.008, respectively; Mann-Whitney test)." (PMID 19116018, 2008).
esophageal squamous cell carcinoma (1 paper, 2025). Esophageal squamous cell carcinoma (ESCC) is a type of esophageal carcinoma (EC) that can affect any part of the esophagus, but is usually located in the upper or middle third. "Mechanistically, ZNF282 functions as a critical coactivator of E2F transcription factor 1(E2F1), transcriptionally upregulating the expression of cyclin A1 (CCNA1) and cell division cycle 6 (CDC6), thereby driving malignant progression in esophageal squamous cell carcinoma (ESCC)." (PMID 41331125, 2025).
Fanconi anemia (1 paper, 2017). Fanconi anemia (FA) is a hereditary DNA repair disorder characterized by progressive pancytopenia with bone marrow failure, variable congenital malformations and predisposition to develop hematological or solid tumors. "Again, DNA repair and cell-cycle-related genes (e.g., Fanca, Brca1, Eme1, Cdc6, Cdc7, Chek1) are enriched (e.g., KEGG terms: Fanconi anemia pathway, homologous recombination, cell cycle, Base excision repair)." (PMID 28638111, 2017).
HCMV infection (1 paper, 2012). "Except for a decrease in Cdt1 and an increase in Cdc6, HCMV infection of quiescent fibroblasts results in little change in the levels of expression of pre-RC proteins." (PMID 22586460, 2012). "It is interesting to note that at IE/early times of HCMV infection these factors are differentially regulated: Cdt1 is downregulated whereas Cdc6 is upregulated." (PMID 22586460, 2012).
head and neck cancer (1 paper, 2024). A primary or metastatic malignant neoplasm affecting the head and neck. "In head and neck cancer, there exist 37 genes such as PPP1R1B and CDC6 with significant association between mRNA abundance and the interaction of the sex and CNAs." (PMID 39011274, 2024).
kidney cancer (1 paper, 2024). Primary or metastatic malignant neoplasm involving the kidney. "CDC6 and CDT1, which act as risk factors for patients’ prognosis, showed a low enough gDS in all kidney cancer cells to show that their deletion severely influences cells’ viability." (PMID 38728235, 2024). "CDC6 and CDT1, especially, represented the lowest gDS in kidney cancer cells, indicating that deletion of these two genes severely affects tumour cell viability." (PMID 38728235, 2024). "Therefore, it is considered that CDC6 and CDT1 promote kidney cancer by regulating these oncogenic pathways." (PMID 38728235, 2024).
large cell lung carcinoma (1 paper, 2022). "The most obvious changed genes in LUAD, LUSC and large cell lung carcinoma were KIAA0101, KIAA0101 and CDC6, respectively." (PMID 36176446, 2022).
liver steatosis (1 paper, 2025). "While our findings and previous literature suggest potential mechanisms by which Smpd3, Dtl, Cdc6, Top2a, and Mki67 contribute to liver steatosis, further study is needed to clarify their precise roles." (PMID 40687776, 2025). "The present study identified five genes (Smpd3, Dtl, Cdc6, Top2a, and Mki67) as potential mediators in the development of WD-induced liver steatosis." (PMID 40687776, 2025).
meningoencephalitis (1 paper, 2022). Inflammation of the meninges and brain, generally secondary to an infectious cause. "TNPO1 (Transportin 1) is involved in checkpoint regulation and CDK-mediated phosphorylation and removal of Cdc6; mutation of TNPO1 leads to retinitis pigmentosa 2 and meningoencephalitis." (PMID 35466186, 2022).
metastatic disease (1 paper, 2023). "CDC6, DHFR, E2F1, H2AFZ, MCM2, GUSB and B2M were significantly higher in patients with metastatic disease than in healthy controls, and CDC6, DHFR and E2F1 were significantly higher in metastatic patients than in localized patients." (PMID 37046768, 2023).
nasopharyngeal carcinoma (1 paper, 2021). A carcinoma arising from the nasopharyngeal epithelium. "In our study, the levels of CDC6 protein were dramatically reduced by MeJA‐treated plants, supporting previous findings where CDC6 was identified as target for radiosensitivity in nasopharyngeal carcinoma." (PMID 33124043, 2021).
oral squamous cell carcinoma (1 paper, 2024). "We also retained several potential multitarget miRNAs for later studies, such as miR-195-5p, which, like miR-26a-5p, also interferes with CDC6 and CCNE1, as demonstrated in oral squamous cell carcinoma cell lines." (PMID 38446584, 2024).
pancreatitis (1 paper, 2015). Inflammation of the pancreas. "The DEGs, including Cdc6, Mcm6, Msh6 and Wdr1 are closely associated with the regulation of caerulein-induced pancreatitis." (PMID 25975747, 2015). "In the current study, Cdc6 and Msh6 were identified as DEGs in wild type and Mist1KO mice, further indicating the importance of these two genes in caerulein-induced pancreatitis." (PMID 25975747, 2015). "In conclusion, high expression of Cdc6 and Mcm6 may lead to increased cell proliferation and pancreatitis." (PMID 25975747, 2015). "Cdc6 is an essential protein for the initiation of DNA replication, and may be highly prevalent in pancreatitis." (PMID 25975747, 2015). "Thus, high expression levels of Cdc6 may lead to increased pancreatic acinar cell proliferation and pancreatitis." (PMID 25975747, 2015).
preeclampsia (1 paper, 2020). Preeclampsia is a hypertensive disorder of pregnancy that is characterized by new-onset hypertension with proteinuria presenting after 20 weeks of gestation, and depending on mild or severe forms may initially present with severe headache, visual disturbances, and hyperreflexia. "CDC6 could regulate the expression of E- and N-Cadherin to affect the migration and invasion of trophoblast cells in preeclampsia." (PMID 32792963, 2020).
renal carcinoma (1 paper, 2024). A carcinoma arising from the epithelium of the renal parenchyma or the renal pelvis. "The protein levels of OTUD6A and CDC6 were also consistent in renal carcinoma tissues." (PMID 38685067, 2024). "Moreover, both the OTUD6A and CDC6 protein levels are increased in BCa and renal carcinoma tumour tissues, and the trend in OTUD6A protein level is consistent with the trend in CDC6 protein level in both BCa and renal carcinoma tissues." (PMID 38685067, 2024).
steatosis (1 paper, 2025). Increased lipid within the cytoplasm of cells. "By integrating data from the two RNA sequencing analyses, we identified five molecules related to cell division: Smpd3, Dtl, Cdc6, Mki67, and Top2a, as key mediators in suppressing WD-induced steatosis in hepAGT −/− mice." (PMID 40687776, 2025). "Increased abundances of Smpd3, Dtl, Cdc6, Mki67, and Top2a were detected after 14 and 42 days of feeding WD, which was consistent with the initiation and advanced phases of steatosis in hepAGT +/+ mice." (PMID 40687776, 2025).
urinary system disease (1 paper, 2023). "CDC6 is also involved in urinary system disease (Association score: 0.79, 23 diseases) and respiratory or thoracic disease (Association score: 0.79, 21 diseases)." (PMID 36599883, 2023).
vascular tumor (1 paper, 2022). "Furthermore, CDC6 was an independent prognostic factor in GC patients with T1-3N1-2M0 staging and no vascular tumor thrombus as presented in the 7th version of the ACJJ (P<0.05)." (PMID 35537781, 2022).
cancer (122 papers, 2007 to 2026). A tumor composed of atypical neoplastic, often pleomorphic cells that invade other tissues. "The TCGA data analysis revealed that CDC6 is overexpressed in most cancers and is associated with a low survival rate in patients with cancer." (PMID 39684684, 2024). "Cell division cycle 6 (CDC6) is a crucial regulator of DNA replication that has been proven to be upregulated in tumors and associated with cancer progression and prognosis." (PMID 38446584, 2024). "Clone 1 had a mutation in CDC6 and only two other mutations, perhaps indicating that its cells more closely resemble normal cells than the cancer cells." (PMID 36813776, 2023). "Over-expression of CDC6 has been detected in several types of cancer, and up-regulation of CDC6 is associated with poor prognosis in cancer patients." (PMID 36232605, 2022). "The results indicated that CDC6 expression in ccRCC tissue was closely associated with individual cancer stage and patients’ race, patients’ gender, patients’ age, tumor grade, KIRC subtypes and lymph node metastasis status." (PMID 34136398, 2021). "Analysis of TCGA data found that CDC6 is overexpressed in most cancers and associates with the poor survival of cancer patients." (PMID 31285446, 2019). "CDC6 overexpression is associated with a low survival rate in many patients with cancer." (PMID 39684684, 2024). "CDC6 has been reported to be associated with the progression and prognosis in various cancers." (PMID 32792963, 2020). "Furthermore, a CRISPR/Cas9 system encoding the GFP reporter gene with a KO target of CDC6 (pSpCas9‐sgCDC6) was used as a therapeutic plasmid to test the cancer cell‐killing effect of gene editing." (PMID 32714743, 2020). "CDC6 overexpression is associated with the poor survival of lots of cancer patients." (PMID 31285446, 2019). "Our findings suggest that CDC6highKI67low may be a new diagnostic and prognostic biomarker, and CDC6 may be a therapeutic target of cancer radiosensitization, which warrant future clinical trials." (PMID 30158672, 2019). "Although Cdc6 is reported to be linked to cancer development, the exactly effects of Cdc6 on malignant progression is still unknown." (PMID 27246979, 2016). "However, the underlying mechanism of CDC6 upregulation in cancer cells is unclear." (PMID 31285446, 2019). "From an integrative analysis of 17 CRISPR/Cas9 libraries, CDC6 emerges as a pivotal biomarker for pan‐cancer ICI response and prognostic stratification." (PMID 39739618, 2025). "In 19 out of 22 (86%) pan‐cancer cohorts, the mRNA level of CDC6 significantly increased in tumor specimens in contrast to those in normal tissues, and this elevated CDC6 expression was associated with unfavorable OS." (PMID 39739618, 2025). "Aberrant upregulation of CDC6 has been found in a broad range of human cancers, including lung cancer, colon cancer, and breast cancer, and correlates with poor prognosis." (PMID 38685067, 2024). "Collectively, these results indicated that OTUD6A promotes the tumorigenicity of human cancer cells by upregulating CDC6." (PMID 38685067, 2024). "We further showed that OTUD6A, through upregulation of CDC6, promotes the proliferation of multiple types of human tumour cells in vitro and tumour growth in vivo, suggesting the importance of OTUD6A-CDC6 axis in these cancer cells." (PMID 38685067, 2024). "Similar to the observations in OTUD6A knockdown and overexpressed cancer cells, knockdown of CDC6 inhibited while overexpression of CDC6 promoted cancer cell proliferation." (PMID 38685067, 2024). "As a regulator of DNA replication, downregulation of CDC6 can inhibit the DNA damage response activity of cancer stem‐like cells." (PMID 39036344, 2024).
cancer (continued). "Gene amplification of CDC6, along with its regulator E2F, is common in tumors with high CDC6 levels, suggesting it plays a significant role in cancer development." (PMID 39052109, 2024). "Our results suggest that CDC6 plays an important role in promoting the abnormal infiltration of immune cells and cancer onset." (PMID 39684684, 2024). "CDC6 can also promote the formation of an immune environment in the development process of some cancers." (PMID 39684684, 2024). "This leads to genomic instability, oncogene activation, and checkpoint replication through the CDC6-ATR-Chk1 signaling pathway in stages that promote cancer cell survival." (PMID 39684684, 2024). "A functional enrichment analysis revealed that CDC6 exerted its pro-cancer and pro-immune cell infiltration functions via the PI3K-AKT pathway." (PMID 39684684, 2024). "In the present study, we found a high expression of CDC6 in both the PCOS and EC samples with carcinomatous tendencies, which is highly consistent with the expression of CDC6 in various cancers." (PMID 39684684, 2024). "Similar to the results obtained in OTUD6A-knockdown cells, knockdown of CDC6 increased the sensitivity of cancer cells to anticancer chemotherapeutic drugs and HU." (PMID 38685067, 2024). "These epigenetic modifications play a significant role in influencing the cancer progression following expression of CDC6 and ORC1 in CRC." (PMID 37945594, 2023). "CDC6 promoted cancer cell growth and enhanced PI3K/AKT signaling and reversed the effect of si-LINC01088 on PCa cells." (PMID 37501932, 2023). "Specifically, CDC6 is known to significantly impact cancer invasiveness by repressing the regulation of E-cadherin." (PMID 37945594, 2023). "High levels of CDC6 in cancers induce DNA over-replication, inhibit apoptosis, and increase tumor invasiveness and metastasis." (PMID 37760529, 2023). "CDC6 activates G2/M phase replication checkpoint through CDC6-ATR-Chk1 signaling to promote the survival of cancer cells." (PMID 37833632, 2023). "Upregulated CDC6 expression was found in tumours, and reduction of CDC6 expression had a strong inhibitory effect on cancer formation and carcinogenesis." (PMID 37594635, 2023). "In SUDHL4 cells, CDC6 knockdown induces cell cycle arrest and apoptosis, which is consistent with previous studies in other cancer types." (PMID 37833632, 2023). "A variety of CDC6 downstream signaling pathways contribute to the dysregulation of cell cycle and proliferation in cancer." (PMID 37833632, 2023). "Cell division cycle 6 (CDC6) is a novel cancer target that regulates the DNA replication process and is considered an early indicator of malignancy." (PMID 37501932, 2023). "In cancer cells, aberrant expression of CDC6 is involved in proliferation and tumor growth by modulating cell cycle." (PMID 35386284, 2022). "When the CRPC cells induced in vitro were treated with Remodelin, Remodelin still showed a strong inhibitory effect on the expression level of CDC6 and the cell proliferation rate of cancer cells." (PMID 35743017, 2022). "CDC6 is found to be reported in initial stages of many cancers and also contributes to the oncogenic activities in tumor development." (PMID 34441816, 2021). "The list of common effects can be therefore extended to reduction in CDC6 activity, a key component in JAs‐suppressed growth in both plant and cancer cells." (PMID 33124043, 2021). "An example target gene CDC6 (a cell-cycle regulator) shows promoter binding of SP1 at these motifs by ChIP-Seq in cancer cells." (PMID 33931649, 2021). "Knockdown of CDC6 slowed cancer cell growth, altered cell cycle progression, and inhibited cell proliferation." (PMID 34440557, 2021).